ESR1 (estrogen receptor 1)
Diseases named in the same sentence as ESR1 in open-access papers (continued):
Sharing a sentence is not in itself a finding about the gene and the disease.
cancer (continued). "Notably, ESR1 mutations are associated with metastases in the liver, a frequent site of disseminated cancer cell growth that is often associated with a poor prognosis in patients." (PMID 41261233, 2026). "The RP2D of 120 mg/day palazestrant demonstrated evidence of antitumor activity, with a CBR of 45.7% and a median PFS of 4.8 months in the overall population and a CBR of 58.6% and a median PFS of 5.6 months among patients with cancers with ESR1 mutations at baseline." (PMID 40598566, 2025). "Similarly, patients with cancers with ESR1 mutations had an extended PFS of 7.3 months and CBR of 59% in this subanalysis." (PMID 40598566, 2025). "Recent studies showed that imlunestrant may be beneficial only for cancers harboring ESR1 mutations." (PMID 40598566, 2025). "Research has shown that cancer-associated, fibroblast-derived exosomes promote the viability, migration, and invasion of GC cells by upregulating the interleukin 32/estrogen receptor 1 (ESR1) axis." (PMID 40601671, 2025). "Genetic studies of ESR1 polymorphisms in cancer are still ongoing." (PMID 40429755, 2025). "Therefore, our pan-cancer genomic analysis demonstrates a positive correlation between ESR1 hotspot mutations and PM." (PMID 41390696, 2025). "Consequently, the effectiveness of endocrine therapy can be compromised when cancer cells harbor activating ESR1 mutations." (PMID 38791941, 2024). "The Y537S mutation in the ESR1 gene may also lead to the situation in which cancer cells start to migrate, contributing to distant metastases." (PMID 37835383, 2023). "Future research prospects may focus on testing the status of the ESR1 mutations as a therapeutic target and can be used as therapies associated with clinical benefits for cancer patients." (PMID 37835383, 2023). "This was also demonstrated with Cox regression analysis, which compared the presence of ESR1 mutations with clinical characteristics such as age, previous neoadjuvant or adjuvant therapies, ER or PR expression, and mitotic index (Ki67) in primary cancer." (PMID 36831647, 2023). "In general, ESR1 gene expression has a similar pattern to ERα immunoexpression, with a loss of gene and receptor expression in high-grade carcinomas, and lower protein scores in more aggressive carcinomas compared with benign tumors and normal mammary glands." (PMID 36978627, 2023). "As an example, we next applied our isoform annotation pipeline to investigate the predicted functional effects of AS in ESR1 (ERα), a clinical biomarker of hormone-positive breast cancers with several AS isoforms associated with cancer progression or treatment." (PMID 35044822, 2022). "Enriched pathways for upregulated miRNAs included: “Chemical carcinogenesis–receptor activation” (p-value = 0.018) associated with ESR1, FGF18, JAG1, KPNA6, PPARA genes; the pathway “Proteoglycans in cancer” (p-value = 0.089) associated with genes ESR1, FRS2, HIF1A, PDCD4." (PMID 36359024, 2022). "The rates of ESR1 mutation detection are 2.6% to 12.0% in primary cancer when using ddPCR14–16." (PMID 35501333, 2022). "ddPCR assays targeting a larger number of mutations may affect the detection rate of ESR1 mutations in primary cancer." (PMID 35501333, 2022). "We suggest that the detection of ESR1 mutations in primary cancer by ddPCR may help predict failure during the early period of ET and help guide the early use of novel ESR1-mutant-targeting therapy." (PMID 35501333, 2022). "ESR1 encodes estrogen receptor α (ERα), which is overexpressed in some cancers." (PMID 33103257, 2021). "Indeed, ESR1 mutation has been used to monitor the resistance of hormone treatment via liquid biopsy, the measurement of cell-free DNA in the blood of cancer patients." (PMID 34795255, 2021). "ESR1 overexpression modulated genes associated with cancer pathways." (PMID 34881186, 2021).
cancer (continued). "In an attempt to search for a surrogate biomarker of prognosis after neoadjuvant hormonal therapy, the tissue samples were tested with EP test, which analyzed the disease-free survival based on the expression levels of proliferative and ESR1 signaling/differentiation-associated cancer genes." (PMID 29158285, 2018). "Table A in S1 File lists over 60 ESR1 SNP variants, sorted by genomic position, showing significant clinical associations with six phenotypic categories in candidate gene studies: Bone/Joint, Cancer, Cardiovascular, CNS, Infection, and Fertility." (PMID 28617822, 2017). "Therefore, we think that further research evaluating the metabolic profiles of ER-positive cancers with ESR1 gene mutations will be needed to identify potential biomarkers associated with poor prognosis of patients with ER-positive cancers." (PMID 28969000, 2017). "Multiple ESR1 variants had been implicated in diverse phenotypes, but causative effects have remained unknown, except for acquired mutations in cancer." (PMID 28617822, 2017). "However, when we examined individual cancer types separately, the methylation-expression association for ESR1 became insignificant." (PMID 23742247, 2013). "In contrast to the findings for all-cause mortality however, current HT was found to greatly increase the risk of cancer-specific mortality for women homozygous TT or AA for ESR1 rs2234693 and rs9340799, respectively, and for those with the GG genotype of ESR2 rs1271572." (PMID 22457817, 2012). "Moreover, the enrichment of APOBEC3 mutagenesis in MBC compared with primary disease has further raised the question of whether APOBEC3 activity is ‘acquired,’ such as ESR1 mutations, or is intrinsic to the evolvable nature of these cancers." (PMID 40379787, 2025). "In addition, ESR1 plays an important role in many immune cells and cancer, a connection that needs further elucidation in the context of T. vaginalis and BV-associated cancer in reproductive systems." (PMID 36985125, 2023). "Additionally, ESR1-associated circRNAs also have been identified in patients with cancer." (PMID 34178027, 2021). "Hence, akin to common cancer types of BC, ESR1, and ERBB2 mutations are present in a mutually exclusive manner in metastatic ILCs, and may constitute mechanisms of resistance to endocrine therapy." (PMID 33083532, 2020). "This discrepancy could potentially be explained by cancers with ESR1 mutations detected in plasma being genetically diverse and more likely to feature other resistant sub clones not assessed here, highlighting the potential importance of understanding heterogeneity with non-invasive assays." (PMID 29497091, 2018). "Women carrying the C allele of ESR1 rs2234693 had a decreased risk of all-cause mortality with HT (HR: 0.42, 95% CI: 0.18–0.97), while in stark contrast, those homozygous for the T allele had a significantly increased risk of cancer-related mortality (HR: 3.18, 95% CI: 1.23–8.20)." (PMID 22457817, 2012). "Women with at least one C or G allele, for the ESR1 rs2234693 and rs9340799 respectively, had a significantly decreased risk of dying from all causes with current HT, while those homozygous TT or AA had a significantly increased risk of cancer-related death with HT." (PMID 22457817, 2012). "Compared to primary BC, cancer cells of BC-BoM were nearly all BC_cells_3 which was characterized by estrogen receptor 1 (ESR1) expression." (PMID 41362730, 2026). "Altogether, these results suggest that GR activation in ESR1 mutant models prolongs animal survival by decreasing liver metastases via a cancer cell-autonomous mechanism." (PMID 41261233, 2026). "To validate the binding of the genes with these four antibodies, we examined 8 candidate genes that are involved in cancer progression, including Esr1, Bcas3, and Bard1, as well as Crebbp, Myc, Rel, Gadd45g, and Shcbp1 (not shown)." (PMID 40157910, 2025).
cancer (continued). "ESR1 activates the expression of genes involved in inhibiting cancer cell proliferation and inducing apoptosis." (PMID 40317014, 2025). "Further research has revealed that ESR1 has an inhibitory effect on the enrichment of cancer stem cells derived from EC cells, and this effect is dependent on the presence of E2." (PMID 40342082, 2025). "A study found that miR-9-5p downregulates ESR1 gene activity in HCC, causing cancer cell proliferation, migration, and invasion." (PMID 41048345, 2025). "Further, the information with respect to somatic mutations in EPHB6 and ESR1 in OSCC is also inadequate; while pooling of these mutations is well documented in other malignant tumours." (PMID 40457841, 2025). "The differential expression patterns and drug sensitivity profiles of CYP1A2, AURKA, and ESR1 highlight their potential significance in the context of immune modulation and cancer therapy." (PMID 40864066, 2025). "Taken together, ESR1 inhibits the enrichment of cancer stem cells derived from EC cells by regulating the effects of E2." (PMID 40342082, 2025). "Next, we analyzed the correlation between AREG and ESR1 using the published Cancer Cell Line Encyclopedia (CCLE) database." (PMID 40422206, 2025). "Prior clinical research suggests a fulvestrant dose response, and patients were treated with extended-dose fulvestrant (500 mg) given every 2 weeks, twice as frequently as standard dosing, to increase fulvestrant exposure and target ESR1 mutant cancers." (PMID 37982575, 2024). "ESR1 was significantly higher in luminal A and luminal B cancer cells in older patients, although estrogen response gene sets did not correlate with age in these cells." (PMID 39483921, 2024). "Our results also indicate that calycosin has the capacity to bind with estrogen receptors ESR1, which makes it widely studied in cancers like breast cancer." (PMID 38254101, 2024). "For this, while cell line-specific responses were not surprising, the integrative analysis of different cell models provides an outlook into cancer diversity and enables to discriminate proteins and pathways common to ESR1 mutants." (PMID 38519482, 2024). "Using data from the Cancer Dependency Map project, we found that sensitivity to TRPS1 knockout correlated with sensitivity to knockout of ESR1, the gene encoding ER." (PMID 38377146, 2024). "For example, we observed that ESR1 and NR2F2, two TFs that are highly mutated in various types of cancer, cooperatively bind to 10 different promoters in our network." (PMID 39013578, 2024). "Camizestrant has demonstrated anti-cancer activity in fulvestrant-resistant ESR1 WT, Y537S, and D538G PDX models." (PMID 39767607, 2024). "TRIM33 offers a novel target for inhibiting estrogen-induced cancer cell growth, particularly in cases of endocrine resistance driven by ER (ESR1) gene amplification or overexpression." (PMID 38473207, 2024). "Clinical, demographic, psychological, cancer treatment-related variables, quantitative sensory testing, and patient genotype (COMT, OPRM1, GCH1, ESR1, and KCNJ6) were assessed as risk factors using multiple logistic regression." (PMID 37184910, 2023). "A statistically significant effect of group in ESR1 mRNA expression was observed, with significant lower ESR1 gene expression in malignant tumors (Group M1–3) compared with normal/hyperplastic mammary tissues (Groups C) and benign CMTs (Group B) (p < 0.001)." (PMID 36978627, 2023). "By contrast, in cancer, the expression of ESR1 oscillates in-phase with the expression of AP2A1, so that expressions of both genes go up or down simultaneously." (PMID 38132440, 2023). "ESR1 is upregulated in NSCLCs favouring cancer survival and progression, whereas it is downregulated in SCLC suggesting that ESR1 binding to LTR30 loci is reduced." (PMID 36918931, 2023).
cancer (continued). "We confirmed the lower level of ESR1 mRNA by qPCR in 44 paired samples of cancer as compared to control endometrial tissue and lower protein levels of ERα by Western blotting with antibodies SP1 in 18 paired samples." (PMID 36769338, 2023). "For instance, the significant expression antagonism (COR(NOR) = −0.96624, p = 0.0338) of AP2A1 (adaptor-related protein complex 2, alpha 1 subunit) with ESR1 in the normal tissue is switched into expression synergism in each of the three cancer nodules." (PMID 38132440, 2023). "A recent analysis of gene expression data from 59 BC cell lines retrieved from the CCLE (Cancer Cell Line Encyclopedia) highlighted an inverse relationship between ESR1 gene expression and HLA genes." (PMID 37894728, 2023). "Conversely, the expression of target ESR1 mRNA was significantly downregulated in malignant tumors compared with both benign CMTs and the normal/hyperplastic mammary gland." (PMID 36978627, 2023). "Based on that AKT1, MAPK3 and ESR1 were included in cancer pathways, as well as AKT1 and MAPK3 included in the PI3K-Akt signaling pathway, the docking results again confirmed the prediction of network pharmacology." (PMID 36034875, 2022). "To further examine the genes and pathways altered between Groups 1 and 2, we performed differential gene expression analysis, adjusting for both cancer type and the ESR1 (ER-α) gene." (PMID 35987928, 2022). "This suggests that the overall lower ESR1 mRNA expression in younger patients is primarily driven by lower ESR1 mRNA levels in ER positive cancer cells." (PMID 36344517, 2022). "ESR1 (estrogen receptor) is closely related to the metastasis of various orthotopic cancers including breast, lung, and prostate." (PMID 35356244, 2022). "For instance, an in vitro study showed that cancer cells with Y537S mutant ESR1 are resistant to fulvestrant but sensitive to potent SERDs, such as AZD949620." (PMID 35501333, 2022). "We propose that the observed ESR1 mutant-cancer cell state interconversions are of potential clinical relevance due to increased stromal immune activation associated with the induction of BCK." (PMID 35440136, 2022). "The results obtained in our study demonstrate that HSA showed a lowering effect on E2 concentration at serum level, and ESR1 at cancer tissues level." (PMID 35386216, 2022). "As Luminal-A cancers are highly dependent on ESR1 activity, we correlated the expression of ESR1 with RP4-568C11.4, and found a strong positive correlation (Figurse 6M,N)." (PMID 36120580, 2022). "ESR1, a protein encoded by the ESRI gene, has shown its association with many kinds of cancers (endometrial, breast, and prostate)." (PMID 35885958, 2022). "In cancer, three other groups emerged with either slightly (class 1), moderately (class 2), or highly increased (class 3) levels of ESR1 mRNA." (PMID 36335194, 2022). "Most of the down-regulated hub proteins (ESR1, MCL1, LCK, TBP, and PCNA) play roles in the proliferation or survival of cancer cells, and CHEK1 is associated with the cell cycle checkpoint in cancer cells." (PMID 35563525, 2022). "For each cancer sample, ESR1 exon expression was also calculated and, similarly to what we observed with BC cell lines, TNBC and MpBC samples showed higher amounts of 5′UTR exon 3a and CDS exons #4–8, compared to #1–3." (PMID 35999225, 2022). "Only in cancer affected tissue, ESR1/SRC and ESR2/PELP1 ratios were both positively correlated with PELP1/SRC (moderately strong) and ESR2/SRC (strong), respectively." (PMID 34207568, 2021). "In the case of ESR1, in tissue obtained from cancer patients, there was a significant correlation with PELP1 and SRC expression." (PMID 34207568, 2021).
cancer (continued). "SRC Cr was moderately and negatively correlated with ESR1/SRC ratios only in tissue affected by cancer." (PMID 34207568, 2021). "Some of these TFs have been shown to exhibit oncogenic properties in various types of cancers, such as ESR1, FOXA1 and E2F1 60–62." (PMID 33850167, 2021). "Our results suggest that the roles of ESR1 in human cancers are more extensive than previously believed and deepen our understanding of ESR1 function in human cancers." (PMID 33865377, 2021). "The analysis of protein–protein interactions according to the STRING database highlighted EGFR and ESR1 as key nodes and endocrine resistance, Th1 and Th2 cell differentiation and proteoglycans in cancer as key pathways within the network." (PMID 33971902, 2021). "Strikingly, the expression of ESR1 (encoding ERα) was correlated with the expression of MIR2052HG in these LCL models, which was in agreement with the analysis of The Cancer Genome Atlas data of 485 ER-positive breast cancer patients." (PMID 34199840, 2021). "The pan-cancer mRNA expression levels, genetic variations, and prognostic values of ESR1, ESR2, and PGR were analyzed using the Gene Expression Profiling Interactive Analysis 2 (GEPIA2) and cBioPortal." (PMID 34322374, 2021). "Mutations in ESR1, ESR2, and PGR genes were the most frequent alterations in multiple cancer types, followed by amplifications and deep deletions." (PMID 34322374, 2021). "Accordingly, methylation of the CpG island in the canine ESR1 gene was studied, comparing normal mammary tissue and malignant tumors." (PMID 33652604, 2021). "Our research found that the active compounds such as quercetin, kaempferol, beta-sitosterol, and stigmasterol (R)-canadine in Scutellaria baicalensis Georgi play an antigastric cancer role by binding ESR1, FOS, and other genes." (PMID 34421596, 2021). "Through this comprehensive pan-cancer analysis, the feasibility of using ESR1, ESR2, and PGR as prognostic markers and therapeutic targets for multiple cancers was evaluated." (PMID 34322374, 2021). "Given the aforemnentioned information, loss of M2 hub ESR1 would be a driver of TFF1 downregulation in TNBC and of increased cancer aggression." (PMID 34007962, 2021). "To identify mutation sites in the ESR1, ESR2, and PGR genes, we assessed 10,189 samples from multiple cancer types." (PMID 34322374, 2021). "While estrogen should activate ERα and stimulate ESR1+ cells, our findings regarding ESR1– cells were important, indicating that the proliferation of ESR1– cells in ER+ cancer is also influenced by estrogen." (PMID 34944995, 2021). "In this study, we conducted a comprehensive pan-cancer analysis of ESR1, ESR2, and PGR on the basis of online databases." (PMID 34322374, 2021). "Esr1 KO females had significantly more carcinomas compared to heterozygous littermates (95% vs 57%; p < 0.026)." (PMID 34068249, 2021). "Many cancers are estrogen-sensitive with neoplastic growth stimulated through the estrogen receptor, ESR1, a transcription factor that regulates developmental genes." (PMID 33255335, 2020). "Numerous miRNAs directly bind with the ESR1 gene to suppress its expression and induce resistance to estrogen/ERα-targeted therapeutic modalities in cancers." (PMID 32759784, 2020). "Considering the fact that AR and ESR1 play a role in cell proliferation and angiogenesis in cancer, it is likely they exert similar functions in placentas." (PMID 33029224, 2020). "While Esr1 was about 2-fold downregulated and Pgr showed zero expression, Erbb2 had a comparable expression in 4T1 vs. the non-cancer mammary gland samples (about 20 TPM)." (PMID 32793490, 2020). "This is further evidence that the ESR1 mutant clone was driving resistance by outcompeting the rest of the cancer cell population through proliferative advantage under hormone therapy." (PMID 32221288, 2020). "For each cancer type, the expression of ESR1 and ESR2 across different patients’ clinical variables were analyzed." (PMID 32536040, 2020).